KRAS (KRas proto-oncogene, GTPase)
Diseases named in the same sentence as KRAS in open-access papers (continued):
Sharing a sentence is not in itself a finding about the gene and the disease.
cancer (continued). "Despite recent breakthroughs in cancer research and translational medicine, the prognosis for patients with advanced-stage CRC remains poor, particularly for patients harboring KRAS mutations." (PMID 41008802, 2025). "The recent identification of KRASG12C inhibitor breaks the “undruggable” curse on RAS and has changed the therapy paradigm of KRAS-mutant cancers." (PMID 39506063, 2025). "Oncogenic KRAS is well-documented to rewire cellular metabolism to meet the high anabolic and redox demands of cancer cells." (PMID 41019978, 2025). "The rat sarcoma (RAS) gene family, comprising HRAS, KRAS and NRAS, is one of the most frequently mutated oncogene families in human cancers." (PMID 40128846, 2025). "The primary developmental functions of KRAS are mediated through the KRAS4B isoform, whereas KRAS4A plays a critical role in cancer progression, possibly through effects on a minor population of stem cells." (PMID 40563429, 2025). "Decades of research on targeting KRAS in cancer have finally removed the “undruggable” tag from the mutant KRAS." (PMID 40131933, 2025). "Our experimental data confirmed the expected changes in the expression of most genes in the CRC‐MT and ‐KRAS‐WT cancer cell lines." (PMID 40013338, 2025). "Elevated basal and minimal activatable autophagy is a common phenotype of KRAS‐driven, autophagy‐addicted cancers." (PMID 40657934, 2025). "SHP2/KRAS coinhibition alters cancer cell signaling and modulates adaptive resistance to KRAS inhibition." (PMID 41309533, 2025). "These aspects are a challenge to the penetration of PDAC and delivery of therapies, such as antibodies.The RAS protein is frequently mutationally activated (HRAS, KRAS, and NRAS) in human cancer." (PMID 40002297, 2025). "After summarization of the immune microenvironment of KRAS mutant cancer, we highlighted the heterogeneity between different types of KRAS mutation." (PMID 40611261, 2025). "Our findings demonstrated that RLY01 effectively suppressed the clonogenic growth of KRAS-mutant cancer cells." (PMID 40091835, 2025). "As a master regulator of multiple cancer-promoting pathways, KRAS itself is under tight regulatory control at different levels of the signaling pathway." (PMID 41309533, 2025). "In KRAS-induced cancer cells, mitochondrial fission is upregulated through the promotion of Drp1 serine 616 phosphorylation and Drp1 activation via the overexpression of Kras and the activation of the MAPK pathway." (PMID 40943457, 2025). "We identified widespread mutations in stem cell-related genes, particularly the high frequency of KRAS mutations (29%), which aligns with previous studies emphasizing the central role of KRAS in cancer stem cell biology." (PMID 40766320, 2025). "The KRAS G12C mutant protein inhibitor, a KRAS inhibitor, has shown high efficacy in mitigating drug resistance and slowing cancer progression." (PMID 40943615, 2025). "Different from GO and KEGG analyses, here, five hallmarks were enriched in LS carcinomas when hypermethylated DMPs were used as an input, including, e.g., KRAS signaling up." (PMID 40753397, 2025). "Adenomatous LST-G exhibits both high-frequency KRAS mutations and metaplastic differentiation, suggesting a potential trajectory for adenomatous LST-G to develop into carcinoma." (PMID 41018078, 2025).
cancer (continued). "This pathway is believed to differ from the traditional AD–carcinoma sequence, in which ADs progress to invasive colorectal carcinomas through a series of genetic changes, including mutations in APC and KRAS." (PMID 40693022, 2025). "At the same time, in our study, KRAS mutant carcinoma was also found to be heterogeneous with the prevalence of IE TME and less frequent inflamed immune contexture." (PMID 40809430, 2025). "Targeting KRAS‐mutant carcinomas is also challenging due to the tissue‐specific pattern of KRAS codon mutations." (PMID 40013338, 2025). "KRAS mutations were found in 32% of the FAP samples (24% of LG adenomas and 78% of HG adenomas and carcinomas), while BRAF mutations were found in only 3% of all samples (serrated tumors were excluded from the analysis)." (PMID 41488735, 2025). "KRAS and NRAS, two GTPase proteins encoded by RAS family member genes, play crucial roles in cancer development." (PMID 39624124, 2024). "Endometriotic lesions also harbour cancer driver mutations such as PIK3CA, PTEN, ARID1A, KRAS, PPP2R1A, and β-catenin (CTNNB1)." (PMID 38893278, 2024). "At present, there are ~30 active clinical trials involving G12Ci MRTX849 or AMG510 in KRAS-G12C–mutant cancers." (PMID 39661665, 2024). "It was worth noting that CDK9i robustly and consistently induced the activation of ERK, an important target of PP2Ac, in KRAS‐mutant cancer cells." (PMID 39254172, 2024). "Result in the production of memory T cells that retain KRAS-specific antigens, reducing the chances of cancer recurrence." (PMID 39720730, 2024). "The KRAS gene has undergone extensive investigation for several decades, with its pivotal involvement in the pathogenesis and progression of various cancers presenting substantial avenues for research." (PMID 38706597, 2024). "Looking ahead, the field stands on the cusp of significant breakthroughs with the potential to revolutionize the treatment paradigm for KRAS-mutant cancers." (PMID 39252322, 2024). "Taken as a whole, KRAS-driven cancers have a plethora of alternative pathways by which their oncogenic programs in the absence of mutant KRAS can be restored." (PMID 38668053, 2024). "Preclinical studies of KRAS- and BRAF-mutated CRC noticed the necessity of dual inhibition of MEK and PIK3CA pathways in the animal model of cancer." (PMID 39056802, 2024). "Cancers driven by KRAS mutants often show significant resistance to conventional and targeted chemotherapies, making them particularly challenging to treat." (PMID 39850800, 2024). "Our study proposes a novel combination therapy for KRAS-G12C mutant cancers utilizing two clinically approved drug classes, namely KRAS-G12C inhibitors and farnesyl-transferase inhibitors." (PMID 38278976, 2024). "Our computational analysis underscores how statins-induced inhibition of protein prenylation acts synergistically with other cancer-related genetic alterations, primarily KRAS, leading to SL." (PMID 39217242, 2024). "Similar to many other cancer types, LUAD encompasses a diverse array of KRAS mutations and other genetic alterations, underscoring the imperative for personalized therapeutic strategies tailored to specific genotypes." (PMID 39385301, 2024). "This study leverages bibliometric analysis and a comprehensive review of clinical trials to identify emerging immunotherapies and potential treatments for KRAS-related cancers." (PMID 39252322, 2024). "In KRAS-mutated cancers, the combination of FAK inhibitors and KRAS G12C inhibitors exhibits promise in reducing drug resistance." (PMID 38273343, 2024).
cancer (continued). "Specifically, this compound significantly downregulated the metabolic pathways in KRAS mutant cancer cells." (PMID 38982514, 2024). "Current inhibitors only target KRAS G12C mutants, but the non-G12C mutants constitute the most in KRAS driven cancers." (PMID 38647154, 2024). "The main finding of the present study is that both VC enantiomers have a comparable capacity in the induction of oxidative stress in KRAS mutant cancer cells, but the D-VC injections in high doses are less toxic in mice compared to its natural form, L-VC." (PMID 38473779, 2024). "Despite these promising advances, there is currently no approved SOS1 inhibitor, and most of these candidates are designed to be combined with anti-cancer drugs targeting the KRAS-MAP kinase pathway." (PMID 38665844, 2024). "Cluster of keywords in co-occurrence analysis in the research of KRAS-related cancer during 2013 to 2022." (PMID 38706597, 2024). "Our data revealed that TKD selectively binds to KRAS in cancer cells and effectively induces KRAS degradation via a lysosome-dependent process." (PMID 38937452, 2024). "To clarify the specific signaling pathways regulated by CD44, we performed GSEA and confirmed that CD44 mainly participated in inflammatory responses, interferon, interleukin, EMT, and KRAS signaling pathways in pan-cancer." (PMID 38590654, 2024). "In this study, we leverage isogenic STAT3 intact and deficient cells to more fully delineate the effects of STAT3 on oncogenic KRAS dependency and the growth of cancer cells in culture or as tumors." (PMID 38573819, 2024). "We also summarized ongoing trials and analyzed emerging perspectives on targeting KRAS in cancer patients." (PMID 38397927, 2024). "Four isoforms of the RAS protein are found in humans: HRAS, NRAS, KRAS4A, and KRAS4B, with RAS mutations detected in 19% of cancer patients (75% in KRAS, 17% in NRAS, and 7% in HRAS)." (PMID 39301544, 2024). "Before the advent of direct KRAS inhibitors, various strategies were explored to target KRAS-driven cancers." (PMID 39594840, 2024). "Together with our recent study and here, the findings support that combination inhibition of SUMOylation and MEK comprehensively conquers MYC-expressing KRAS-mutant cancers by both immune-dependent and immune-independent antitumor responses." (PMID 39334463, 2024). "Collectively, our studies provide important insights into KRAS biology and reveal a critical role for wild-type KRAS in the therapeutic resistance of KRAS-driven cancers." (PMID 38168062, 2024). "Understanding the function of wild-type KRAS is essential to identify effective therapeutic strategies for oncogenic KRAS-driven cancers and potential mechanisms of resistance to KRAS targeting therapies." (PMID 38168062, 2024). "Then, when comparing the mutation frequencies of major cancer driver and immune evasion-related genes between the CIMP subgroups in MSI-H CRCs, KRAS mutation was the only significant factor." (PMID 39235590, 2024). "Values were close to what was demonstrated in a CRC study in Latin American patients, where 30% of patients (85 patients) had the KRAS test and 40.0% (34 patients) had KRAS mutant cancers." (PMID 39728065, 2024). "This publication aims to explore KRAS-related cancer research, enable researchers to understand the development history and extract the most essential information from the massive research." (PMID 38706597, 2024). "These acquired mutations were also observed in a clinical study that included KRAS G12C-mutant cancer patients treated with adagrasib in monotherapy, of whom 71% were NSCLC patients." (PMID 38846975, 2024). "Taken together, these findings suggest that this combination mechanistically blocks DSB repair, resulting in the accumulation of DNA damage and the induction of apoptosis in MYC-expressing KRAS-mutant cancers." (PMID 38992694, 2024).
cancer (continued). "KRAS mutations, typically seen on codons 12, 13, or 61, result in constitutive activation of the KRAS protein, which can ultimately lead to cancer." (PMID 38667294, 2024). "KRAS is an important predictive pharmacogene of cancer and is one of the most frequent gain-of-function alterations found in patients with cancer." (PMID 38397135, 2024). "In this study, different machine learning models were used to identify new promising hits from the ZINC database against the KRAS G12D cancer drug target." (PMID 38794122, 2024). "Mutations in NRAS, KRAS, and HRAS are found in 20% of cancers, with KRAS being the most frequently mutated protein (15%)." (PMID 38473265, 2024). "One possible explanation is the independence of mutant KRAS cancer cells from KRAS oncogenic signaling." (PMID 39061234, 2024). "In recent years, there has been a growing body of evidence indicating the presence of somatic mutations in cancer-associated genes including ARID1A, PIK3CA, KRAS, or PPP2R1A in endometriotic lesions." (PMID 38600147, 2024). "Here, we found that cancer cells resistant to KRAS G12C inhibitors also display cross-resistance to other targeted therapies, such as inhibitors of RTKs or SHP2." (PMID 39704172, 2024). "In the case of radiotherapy, the major treatment of NSCLC, hypoxia due to disorganized vasculature, cancer stem cells and mutational status (e.g., EGRF, KRAS, etc.)are believed to be among the key factors in resistance." (PMID 38793058, 2024). "The molecular genetic somatic mutation research in cancer plays an essential role and the presence of mutated genes that belong to the Ras subfamily (e.g., KRAS, NRAS, HRAS) allows for the detection of several cancer types." (PMID 38539435, 2024). "Our previous works validated the efficacy of KRAS- and MYC-targeting PPRHs, which provoked gene silencing and resulted in the death of cancer cells with deregulated KRAS and/or MYC." (PMID 39457457, 2024). "Precision medicine has drastically changed cancer treatment strategies including KRAS-mutant cancers which have been undruggable for decades." (PMID 39334463, 2024). "This was observed in 90.9% of KRAS in CRA (30 out of 33 mutations) and 86.4% in CRC‐I (19 out of 22 mutations), underscoring the critical role of these hotspots in cancer progression." (PMID 39554798, 2024). "Although similar mutations in other cancers, such as ALK, EGFR, and KRAS in lung cancer or BRAF in melanoma, have revolutionized cancer treatment, identifying analogous markers in GBC is challenging due to its genetic heterogeneity." (PMID 39683528, 2024). "By performing a co-citation analysis of references through CiteSpace, we delineated the temporal landscape and evolving trends of research focused on KRAS-induced immunotherapy in cancer." (PMID 39252322, 2024). "Though there is not enough space in the present context to discuss those factors of the Wnt signaling pathway, our focus is mainly on the cross-talk between KRAS and the Wnt pathway driver factor and regulation of cancer." (PMID 39056802, 2024). "GSEA was subsequently performed, and the results revealed that DEGs from the high-risk group were enriched in pathways related to the promotion of cancer, such as epithelial–mesenchymal transition, hypoxia, and KRAS signalling." (PMID 38553479, 2024). "The CRISPR/Cas system has demonstrated its potential for basic and translational cancer research, particularly in the mechanistic understanding of KRAS biology and the development of KRAS-mutant cancers." (PMID 38275900, 2024). "RAS genes (KRAS, HRAS, NRAS) are the most frequently mutated oncogene family, with mutations occurring in 19% of patients with cancer." (PMID 38800401, 2024).
cancer (continued). "GATA3 has also been proposed to transactivate miR-181a/b1 promoter in mutant KRAS–induced cancers, in which TGF-β signalling was involved." (PMID 39120319, 2024). "Collectively, our data suggest that downregulation of AURKA in KRASG12C inhibitor–treated cancer cells induces Hh signaling and re-expression of KRAS." (PMID 38225225, 2024). "Recent integrated genomic profile analyses of the major cancer mutation databases have shown that approximately one out of seven human cancers harbours KRAS gene alterations, making it one of the most frequently mutated genes." (PMID 38261067, 2024). "Among RAS mutant cancer cell lines, KRASG12X and NRAS glutamine 61 mutant (NRASQ61X) cells were significantly more sensitive compared with cell lines with other oncogenic KRAS or NRAS mutations, respectively (Wilcoxon rank-sum test with continuity correction)." (PMID 38593348, 2024). "Overall, our findings underscore the potential of co-administering a SOS1i with allele-specific KRAS inhibitors to improve and prolong clinical responses in patients with cancer driven by mutant KRAS." (PMID 39103541, 2024). "This high prevalence is significant as it makes PDAC arguably the most RAS-addicted cancer, with substantial experimental evidence that mutant KRAS is essential for its growth." (PMID 38666907, 2024). "Mutations and polymorphisms of the KRAS and NRAS genes have been linked in certain studies to increased cancer aggressiveness, a greater recurrence rate, and a worse response to platinum treatments in patients with LSCC." (PMID 39867023, 2024). "The investigation provides mechanistic and preclinical evidence that substantiates the potential therapeutic effects of this approach for treating KRAS-mutant cancers." (PMID 38409090, 2024). "In both the control as well as in cancer patients it was found a positive correlation between KRAS and SMARCA4 (p = 0, R = 0.95 and p = 0, R = 0.84 respectively)." (PMID 38446332, 2024). "SOS1 catalyzes the formation of KRAS-GTP complex to activate multiple downstream signaling pathways that trigger cancer cell proliferation." (PMID 38734764, 2024). "We utilized CiteSpace to create a keyword co-occurrence graph, designed to unveil the relationship among terms and thereby identify the seminal content and emergent hotspots in the domain of KRAS-induced cancer immunotherapy." (PMID 39252322, 2024). "KRAS (Kirsten rat sarcoma viral oncogene homolog) plays a key role in the development and progression of various cancers, including NSCLC." (PMID 39156705, 2024). "This study adds to the ongoing efforts to address the therapeutic hurdles presented by KRAS in cancer treatment." (PMID 39001451, 2024). "While targeting downstream MAPK signaling proves effective for certain cancer types and stands as the standard treatment for patients with BRAFV600E activating mutations, this approach has proved largely ineffective for KRAS mutant cancers." (PMID 39164274, 2024). "The BAY 11-7082 treatment exerts a broad-spectrum impact, mechanistically altering various pathways in cancer cells harboring NRAS, KRAS, and HRAS mutations." (PMID 38982514, 2024). "Strikingly, treatment with conditioned media of activated fibroblasts attenuated the differences in cancer stem cell expression previously observed between the control and KRAS-silenced cells." (PMID 39061234, 2024).